BRF2 (BRF2 general transcription factor IIIB subunit)
Diseases named in the same sentence as BRF2 in open-access papers (continued):
Sharing a sentence is not in itself a finding about the gene and the disease.
breast carcinoma (continued). "Further query of the Breast Cancer METABRIC, for patients aged 55–60 with BRF2 alterations, ER positive status (n = 170) correlated with a decrease in overall survival, p = 7.87e-3, whereas ER negative status (n = 59) did not, p = 0.516." (PMID 33176745, 2020). "To elucidate if BRF2 alterations co-occur with alterations in known oncogenes and biomarkers in IBC we analyzed copy-number alteration frequency in breast cancer patients with BRF2 alterations." (PMID 33176745, 2020). "The median gene rank and COPA scores for BRF2 and HER2 are comparable in the meta-analysis of 3594 breast cancer patients included in this analysis." (PMID 33176745, 2020). "In vitro experiments provided functional evidence to suggest that BRF2 and DSN1 overexpression/amplification, and the HER2 I767M mutation may be alterations that compensate for the lack of HER2 amplification in the HER2-negative components of HER2 heterogeneous breast cancers." (PMID 25994018, 2015). "These analyses revealed that there were no strong correlations between the expression of BRF2 in breast cancer datasets and the selected features of genomic instability." (PMID 34359683, 2021). "Similarly, in breast cancer lines, MDA-MB-231 and SUM159PT, using a longer time course of up to 24 h, we observed a similar rapid and persistent upregulation of BRF2 upon DNA damage." (PMID 34359683, 2021). "Expression of BRF2 RNA and protein was assayed in ER-positive or –negative human breast cancer cells after exposure to daidzein." (PMID 26573593, 2015). "The expression of TFIIIB components BRF1, BRF2 and BDP1 was in tendency higher in luminal subtypes, that of most TFIIIC components (C2-C6) in Her2-overexpressing cancer, but none of these general Pol III transcription factors showed increased expression levels in basal breast cancers." (PMID 36497214, 2022). "Hence, we sought to define whether BRF2 and DSN1 would have oncogenic properties in in vitro models of breast cancer." (PMID 25994018, 2015). "The breast cancer biomarkers ERBB2 (HER2), ESR1(ER), PIK3CA are not significantly altered in patients with BRF2 alterations." (PMID 33176745, 2020). "From this list of genes, we focused on BRF2 and DSN1, given the lack of direct functional evidence to support a potential oncogenic role of the amplification of these genes in breast cancer." (PMID 25994018, 2015).
lung squamous cell carcinoma (12 papers, 2010 to 2025). "The genetic activation of BRF2 has also been linked to lung squamous cell carcinoma and other cancers." (PMID 34359683, 2021). "Of note BRF2 has the highest associated HR, and was recently identified as a putative oncogene in squamous cell lung cancer." (PMID 22719901, 2012). "The results showed that BRF2 was highly expressed in lung squamous cell carcinoma tissues and cells." (PMID 40610422, 2025). "In TIMM23-knockdown human embryonic kidney 293 T (HEK293T) cells, undegraded PINK1 accumulated, whereas TIMM23 expression remained unchanged in lung squamous cell carcinoma cell lines H226 and H520 despite variations in BRF2 and SLC8A3 levels." (PMID 40610422, 2025). "William Lockwood and colleagues show that the focal amplification of a gene, BRF2, on Chromosome 8p12 plays a key role in squamous cell carcinoma of the lung." (PMID 20668658, 2010). "BRF2 is frequently activated during the invasion stage of lung squamous cell carcinoma." (PMID 36927769, 2023). "Recently, BRF2, a component of TFIIIB required for gene external RNA pol III transcription, was identified as an oncogene in squamous cell carcinomas of the lung through integrative genomic analysis." (PMID 21518452, 2011).
squamous cell carcinoma (6 papers, 2010 to 2025). A carcinoma arising from squamous epithelial cells. "BRF2 expression was upregulated in squamous carcinoma cells, which increased SLC8A3 protein expression, promoted mitochondrial autophagy, stabilized MMP, and reduced apoptosis." (PMID 40610422, 2025). "Artificially induced expression of BRF2 in bronchial epithelial cells made these normal cells behave like tumor cells, whereas reduction of BRF2 expression in squamous carcinoma cells made them behave more like normal bronchial epithelial cells." (PMID 20668658, 2010). "Only one of the genes—BRF2—was more highly expressed in squamous carcinoma cells than in normal bronchial epithelial cells (the cell type that lines the tubes that take air into the lungs and from which SqCC develops)." (PMID 20668658, 2010). "Finally, BRF2 was frequently activated in two early stages of squamous cell carcinoma—bronchial carcinoma in situ and dysplastic lesions." (PMID 20668658, 2010).
lung adenocarcinoma (4 papers, 2014 to 2023). A carcinoma that arises from the lung and is characterized by the presence of malignant glandular epithelial cells. "A549 are epithelial human lung adenocarcinoma cells displaying high Brf2 expression and a generally increased resistance to t-BHP treatment when compared to MRC5 fibroblasts." (PMID 26638071, 2015). "Furthermore, Let-7b-3p inhibits proliferation and metastasis of lung adenocarcinoma cells in vivo and in vitro by directly targeting the BRF2-mediated MAPK/ERK pathway." (PMID 36791156, 2023). "Certainly, in lung adenocarcinoma (LUAD) cells and tissue samples let-7b-3p was down-regulated that is in relation with poor prognoses in LUAD patients while targeted the BRF2-mediated MAPK/ERK pathway." (PMID 37813634, 2023).
esophageal squamous cell carcinoma (3 papers, 2020 to 2023). Esophageal squamous cell carcinoma (ESCC) is a type of esophageal carcinoma (EC) that can affect any part of the esophagus, but is usually located in the upper or middle third. "In many cancers, such as esophageal squamous cell carcinoma, adrenocortical carcinoma, invasive breast carcinoma, NSCLC, bladder carcinoma, and sarcoma, BRF2 is often amplified and/or gained through copy number alterations." (PMID 34359683, 2021). "Interestingly, BRF2 expression is an independent prognostic factor for overall survival (p = 0.014) and biomarker for progression-free survival (p = 0.014) for patients with esophageal squamous cell carcinoma (ESCC) undergoing three-field lymph-node dissection (3FLND) treatment." (PMID 33176745, 2020).
invasive breast carcinoma (3 papers, 2015 to 2021). A carcinoma that infiltrates the breast parenchyma. "In this study, we demonstrate MYC and BRF2 alterations co-occur in breast invasive carcinoma, p = 0.008, as well as patients aged 46–50 with metastatic breast cancer, p = 0.053." (PMID 33176745, 2020). "The authors queried both Oncomine and cBioPortal for alterations in BRF2 in human cancers and performed meta-analyses identifying significant correlations between BRF2 and clinical outcomes in invasive breast cancer (IBC)." (PMID 33176745, 2020). "Herein, we report for the first time, a possible role for BRF2 as a prognostic marker in invasive breast cancer (IBC)." (PMID 33176745, 2020). "The cBioPortal cancer genomics database reveals amplification of the BRF2 gene in 12 % of 825 tumors in the Breast Invasive Carcinoma study (TCGA, Nature 2012)." (PMID 26573593, 2015). "Notably, there is a 2.3-fold increase in BRF2 mRNA expression in Intraductal Cribriform Breast Adenocarcinoma, a form of invasive breast carcinoma, as compared to controls, p = 9.34E-7." (PMID 33176745, 2020). "This study suggests BRF2 may be an prognostic biomarker in invasive breast carcinoma." (PMID 33176745, 2020). "To determine if the observed alterations in BRF2 and MYC are mutually exclusive or co-occur in breast invasive carcinoma we queried the IBC data set, TCGA, Firehose Legacy in the cBioPortal." (PMID 33176745, 2020). "In the cBioPortal Breast Invasive Carcinoma (TGCA, Firehose Legacy) data set, MYC alterations correlated with a decrease in overall survival, p = 0.0918 and co-occurring MYC and BRF2 alterations significantly decreased overall survival, p = 5.299e-3." (PMID 33176745, 2020).
leukemia (3 papers, 2011 to 2020). A malignant (clonal) hematologic disorder, involving hematopoietic stem cells and characterized by the presence of primitive or atypical myeloid or lymphoid cells in the bone marrow and the blood. "BRF2 is overexpressed in both the leukemia (1 significant of 233 unique analyses) and lymphoma (1 significant of 233 unique analyses) data sets and underexpressed in a liver cancer (1 significant of 233 unique analyses) data set." (PMID 33176745, 2020). "Further query of the information presented in the BRF2 disease summary demonstrated that in analyses comparing multi-cancers, "cancer versus cancer", BRF2 is overexpressed in both leukemia and lymphoma as well." (PMID 21518452, 2011).
melanoma (3 papers, 2011 to 2020). A malignant, usually aggressive tumor composed of atypical, neoplastic melanocytes. "Fold change in BRF2 expression (cancer versus control) and sample numbers in melanoma, gastric and kidney cancers data sets remains unchanged as previously reported and data is not shown." (PMID 33176745, 2020). "Like that of BRF1, expression of BRF2 was increased when primary human IMR90 fibroblasts were transformed with successive defined genetic steps, and BRF2 expression was found increased in Oncomine data sets from melanoma as well as gastric and kidney cancers." (PMID 32611613, 2020).
non-small cell lung carcinoma (3 papers, 2014 to 2021). A group of at least three distinct histological types of lung cancer, including non-small cell squamous cell carcinoma, adenocarcinoma, and large cell carcinoma. "BRF2 knockdown can inhibit the migratory and invasive abilities of non-small cell lung cancer cells (NSCLCs) and induce the loss of the epithelial-mesenchymal transition." (PMID 34359683, 2021). "Recently, studies identified BRF2 as a prognostic marker of unfavorable survival for both squamous cell carcinoma (SqCC) (p = 0.007) and non-small cell lung cancers (NSCLC) (p = 0.001), as well as esophageal cancers (p = 0.009)." (PMID 33176745, 2020). "Both BRF2 protein and intratumoral microvessels were examined by immunohistochemical staining in 107 non-small cell lung cancer patients." (PMID 24523874, 2014). "The aim of this study was to examine BRF2 expression in patients with non-small cell lung cancer (NSCLC) and explore the relationship of BRF2 protein with clinicopathologic factors, tumor angiogenesis and prognosis." (PMID 24523874, 2014).
breast tumors (2 papers, 2015 to 2021). "Notably, we found that BRF2 amplification was mutually exclusive to the loss of BRCA1 and BRCA2 in breast tumors, both in the TCGA and METABRIC datasets." (PMID 34359683, 2021). "A recent report has noted a context-dependent oncogenic role for BRF2 (not a known oncogene in most cancers) in driving a subset of HER2+ breast tumours which do not express ERRB2/HER2; the authors call BRF2 an ‘alternative driver’ of HER2+ tumours." (PMID 26427375, 2015).
hepatocellular carcinoma (2 papers, 2020 to 2025). A malignant tumor that arises from hepatocytes. "Furthermore, BRF2 promotes hepatocellular carcinoma invasion and metastasis through the Wnt/β-catenin pathway." (PMID 40610422, 2025).
kidney cancer (2 papers, 2020). Primary or metastatic malignant neoplasm involving the kidney. "Specifically, in the cancer histology data set for kidney cancer, BRF2 is both overexpressed (3 significant of 630 unique analyses) and underexpressed (2 significant of 630 unique analyses)." (PMID 33176745, 2020).
liver cancer (2 papers, 2020 to 2023). An epithelial or non-epithelial malignant neoplasm that arises from the liver. "Relative levels of BRF2 mRNA were significantly increased in liver cancer tissues compared with normal liver tissues according to bioinformatic analysis of several databases." (PMID 36927769, 2023). "Consistently, we observed increased BRF2 mRNA levels in liver cancer tissues compared with the adjacent normal tissues in clinical specimens." (PMID 36927769, 2023).
prostate carcinoma (2 papers, 2008 to 2025). A carcinoma that arises from epithelial cells of the prostate gland. "Interestingly, we have observed that Brf2 protein levels may correlate with U6 snRNA transcription rates in the breast, cervical and prostate cancer cell lines tested." (PMID 18700021, 2008).
sarcoma (2 papers, 2020 to 2021). A usually aggressive malignant neoplasm of the soft tissue or bone. "In this study, we demonstrate BRF2 overexpression in cancers of the breast, stomach, kidney, skin, and sarcoma." (PMID 33176745, 2020). "BRF2 overexpression in sarcoma was observed in the Cho Gastric Stroma data set, n = 80 samples and p = 9.965E-5." (PMID 33176745, 2020). "In addition, BRF2 is also significantly overexpressed in sarcoma, 1 significant of 5 (20%) unique analyses." (PMID 33176745, 2020).
breast adenocarcinoma (1 paper, 2020). "There is a 2.3-fold increase in BRF2 mRNA expression in intraductal cribriform breast adenocarcinoma as compared to controls." (PMID 33176745, 2020).
bronchial carcinoma in situ (1 paper, 2010). "Frequent activation of BRF2 in >35% preinvasive bronchial carcinoma in situ, as well as in dysplastic lesions, provides evidence that BRF2 expression is an early event in cancer development of this cell lineage." (PMID 20668658, 2010).
ductal carcinoma (1 paper, 2020). "The average estimated copy number for BRF2 in ductal carcinoma is 2.28, with 42% having an estimated copy number greater than 2.0." (PMID 33176745, 2020).
esophageal cancer (1 paper, 2023). A primary or metastatic malignant neoplasm involving the esophagus. "Many studies have shown BRF2 to be an oncogene in numerous solid tumors, including lung, gastric, and esophageal cancers, and its expression has been shown to correlate with worse clinical outcomes." (PMID 36927769, 2023).
fibrosarcoma (1 paper, 2021). A malignant mesenchymal fibroblastic neoplasm affecting the soft tissue and bone. "The exposure of MCF10A cells, a near-normal mammary epithelial cell line derived from human fibrosarcoma, to different doses of γ-irradiation showed a marked increase in BRF2 expression when harvested 1 h after exposure." (PMID 34359683, 2021).
gastric cancer (1 paper, 2021). A primary or metastatic malignant neoplasm involving the stomach. "Although the role of BRF2 has not been characterized in gastric cancer, it can be seen that miR-527 is a biomolecule at a key position in tumorigenesis and development." (PMID 33472586, 2021).
gastrointestinal stromal tumor (1 paper, 2020). "BRF2 mRNA expression was increased 2.4-fold in gastrointestinal stromal tumors as compared to controls." (PMID 33176745, 2020).
leukodystrophies (1 paper, 2025). "These two, as well as other RNA polymerase III subunits, were also linked to hypomyelination leukodystrophies, while BRF1, the BRF2 paralog, was associated with CFDS." (PMID 40229899, 2025).
Miscarriage (1 paper, 2025). A pregnancy that ends at a stage in which the fetus is incapable of surviving on its own, defined as the spontaneous loss of a fetus before the 22th week of pregnancy. "Couples heterozygous for the BRF2 splice variant did not have a higher risk of miscarriage compared to non-carrier couples matched on year of birth (OR = 2.14 [95%CI 0.82, 5.55], P = 0.094, N carrier couples = 21, N miscarriage = 10)." (PMID 40229899, 2025).
ovarian carcinoma (1 paper, 2023). A malignant neoplasm originating from the surface ovarian epithelium. "BDP1 mRNA expression was significantly decreased in ovarian cancer, p = 0.01 but the expression of other TFIIIB subunits, BRF1, BRF2, and TBP, was not significantly changed." (PMID 36305848, 2023).
serous ovarian cancer (1 paper, 2023). "We sought to determine if the observed alterations in BDP1 in serous ovarian cancer are unique to BDP1 or are a common feature in all TFIIIB subunits including, BRF1, BRF2, and TBP which have been previously shown to be deregulated in cancer." (PMID 36305848, 2023).
cancer (25 papers, 2008 to 2025). A tumor composed of atypical neoplastic, often pleomorphic cells that invade other tissues. "These discoveries reveal that BRF2 plays a critical role in various tumors, and is closely linked to the invasion and migration of cancer cells." (PMID 36927769, 2023). "Next, we analyzed the correlation between BRF2 expression and 18 features (measures) of genomic instability, a hallmark of cancer." (PMID 34359683, 2021). "Accordingly, miR-373 overexpression or BRF2 knockdown in cancer cells (A549 cells) impairs proliferation, migration, and invasion." (PMID 35884580, 2022). "In lung cancer, the lncRNA MNX1-AS1 promotes cancer progression by interacting with miR-527, thereby preventing miR-527-induced BRF2 downregulation." (PMID 35884580, 2022). "Comparison of RNA Seq data of gene expression levels in normal and tumor tissues in 32 cancer types reveals that BRF2 is significantly overexpressed in many tumor types, including malignancies of the breast, lung, liver, and kidney." (PMID 34359683, 2021). "Conversely, Brf2 knockdown in A459 cancer cells, in which the Nrf2 pathway is overactivated and Brf2 overexpressed, leads to cell death." (PMID 34202320, 2021). "To further validate this, we performed pan-cancer analysis on BRF2 expression levels and copy numbers using TCGA datasets." (PMID 34359683, 2021). "Recent studies have highlighted a direct link between Brf2 over-expression and many types of cancer, including lung and breast cancer." (PMID 34202320, 2021). "By analyzing multiple TCGA cancer datasets, BRF2 has been shown to be significantly upregulated in an HER2-negative compartment of these tumors to compensate for the lack of HER2 amplification." (PMID 34359683, 2021). "Therefore, it has been speculated that high levels of BRF2 expression in cancer cell lines support the sufficient expression of selenoproteins, in order to detoxify ROS and preserve redox homeostasis, which is a hallmark of cancer cells." (PMID 34359683, 2021). "After initial in silico confirmation, we aimed to identify the drug sensitivity response based on BRF2 gene expression using the genomics of drug sensitivity in cancer (GDSC) database." (PMID 34359683, 2021). "BRF2 senses oxidative stress, and upon exposure to oxidative agents, BRF2-depleted cancer cells undergo oxidative stress-induced cell death, but normal cells avoid this through the upregulation of selenoproteins." (PMID 34359683, 2021). "Given the upregulation of BRF2 in cancer and our findings indicating its link with DNA damage repair, we aimed to target BRF2 by repurposing available drugs." (PMID 34359683, 2021). "Our data thus provide the first experimental evidence that BRF2 is a novel player in the DNA damage response pathway and that bexarotene can be used as a potential inhibitor to treat cancers with the specific elevation of oxidative stress." (PMID 34359683, 2021). "This is indicative of the potential efficacy of Bex, with increasing BRF2 expression in the indicated cancer setting." (PMID 34359683, 2021). "The upregulation of BRF2 in cancer cells confers survival via the prevention of oxidative stress-induced apoptosis." (PMID 34359683, 2021). "Multiple cancer models have also shown significant alterations in BRF2 copy number variations, specifically copy number gain and amplification." (PMID 34359683, 2021). "In conclusion, we showed BRF2 to be a potential therapeutic target in cancer by comprehensively analyzing the publicly available pan-cancer data." (PMID 34359683, 2021). "This safety mechanism is by-passed in cancer: by overexpressing Brf2, cancer cells alleviate this regulation and prevent apoptosis." (PMID 34202320, 2021). "In conclusion, there is a limited correlation between BRF2 expression and cancer hallmarks, signaling pathways, and immune markers." (PMID 34359683, 2021). "This scenario can confirm the anti-cancer effects of this drug in cancers with high oxidative stress that upregulate BRF2 expression." (PMID 34359683, 2021).